IFNG (interferon gamma)
Diseases named in the same sentence as IFNG in open-access papers (continued):
Sharing a sentence is not in itself a finding about the gene and the disease.
tumor (continued). "During recall assays in animals immunized with βhCG-TT + MIP, TT also induced significantly heightened levels of IFNγ and TNFα, cytokines with significant anti-tumor activity." (PMID 23593454, 2013). "Among these cytokines, IFNG, which was discovered in 1965, has a reputation for helping guard against neoplastic disease." (PMID 24244422, 2013). "TNF, IFNγ, IL-6 and IL-11 gene expression were higher in non-tumor tissue from Iron/DSS and Control/DSS mice compared with colonic tissue from Iron and Control mice at day 78 (data not shown)." (PMID 24223168, 2013). "Within the tumor microenvironment of the stomach, pro-inflammatory cytokine interferon-gamma (IFNγ) and Sonic hedgehog (Shh) are elevated." (PMID 24069395, 2013). "Analysis of tumor-infiltrating CD45+ leukocytes showed consistent Lov-mediated upregulation of IFNγ and IL-1β (M1 markers) and downmodulation of IL-10, CD206 and CCL22 (M2 markers)." (PMID 24317954, 2013). "In a murine model of breast cancer, mice treated with IL-12 exhibited differentiation of MDSC at tumor sites, increased overall survival, decreased lung metastasis, and reduced levels of mRNA encoding NO2 and IFNγ." (PMID 24829747, 2013). "There is a close relationship between tumor progression and dysregulation of cytokine expression, as seen for IFNG, TGF-β, and IL-17." (PMID 24244422, 2013). "IL-12p70, which strongly promotes the differentiation of type-1 T-cells, enhances IFNγ and granzyme B production, prolongs T-cell survival and enhances immune recognition of tumor antigen-expressing cells." (PMID 26344346, 2013). "Our data is supported by a previous study showing that secretion of IFNγ by activated NK cells can facilitate the priming of tumor-specific CD8 T cells." (PMID 23738889, 2013). "IFNγ production confirmed dTc activation by KIT+ tumor and was found to be in the range of 462-475 pg/ml, while production by CIR- T cells was negligible (p<0.001)." (PMID 23433424, 2013). "We sorted CD4+ CD25+ (Treg) and CD4+ CD25− (conventional T) T cell subsets from the spleen from PBS- or BLM-treated tumor-bearing mice, and tested their capacity to blunt IFNγ production by OT-I cells in an in vitro assay." (PMID 23762310, 2013). "Recent study showed that IFNG is vital to tumor surveillance by the immune system and that there was a high correlation between IFNG production and tumor regression during immunotherapy." (PMID 24244422, 2013). "The differentiation of naïve T cells into mature CD8 Teff or CD4 Th1 or Th17 cells is required for T cells to make full use of their functional attributes directed against tumor cells, such as cytotoxicity and production of IFNγ and TNFα." (PMID 24265631, 2013). "For one of these patients (mel65), viable and MHC class I expressing autologous tumor cells were available for functional testing by IFNγ secretion assay." (PMID 23402380, 2013). "In contrast, 15 % of spleen iNKT cells isolated from mice treated with tumor-targeted αGC/sCD1d-anti-CEA were positive for IFNγ, which correlated with the fact that antitumor activity was exclusively obtained in this group." (PMID 23242316, 2013). "This IFNγ potentiates several IFNγ dependent chemokines to create a pull for CD8+ T cell movement within tumor milieu." (PMID 23326300, 2013). "Taken together, Ad-IFNγ displayed efficient anti-NPC activities by inhibiting tumor cell proliferation and induced cell apoptosis in this study." (PMID 23272637, 2012). "CD8+ T cells produce interferon-gamma through interaction with tumor-related antigens, potential leading to tumoricidal activity by induction of apoptosis or macrophage tumor killing activity or both." (PMID 22420471, 2012). "The anti-tumor effects and toxicity of Ad-IFNγ were evaluated in BALB/c nude mice carrying NPC xenografts." (PMID 23272637, 2012). "The results showed that Ki-67 was significantly lower in tumor tissue treated with Ad-IFNγ than those in Ad-LacZ group and PBS group." (PMID 23272637, 2012).
tumor (continued). "Based on our observations on increased T and NK cell IFNγ production in the tumor, we evaluated the angiogenic profiles in the tumor." (PMID 22815789, 2012). "Healthy donor T cells were activated to secrete IFNG by phytohemagglutinin (PHA) stimulation in the presence of increasing concentrations of tumor exosomes." (PMID 22848702, 2012). "In our study, we used IFNγ and TNFα stimulating human MSCs from bone marrow to imitate the tumor inflammatory microenvironment, and then co-cultured with different HCC cells." (PMID 22952657, 2012). "In neu-N mice, however, low avidity T cells were unable to reach a level of activation necessary for adequate IFNγ secretion, integrin upregulation, or tumor infiltration." (PMID 22359647, 2012). "Tumor growth in the Ad-IFNγ-treated groups was significantly slower than that in Ad-LacZ (vector control) group or PBS (medium control) group." (PMID 23272637, 2012). "An inhibition of tumor angiogenesis preceded tumor regression in other models of IFNγ mediated rejection of tumors by CD8+ T cells suggesting that IFNγ targeted vascular endothelial cells, fibroblasts, and/or pro-angiogenic macrophages." (PMID 23060881, 2012). "Following inoculation of oHSV in vivo, IFNγ can be produced by resident microglia, recruited macrophages, dendritic and NK cells at the growing tumor site." (PMID 22924042, 2012). "Sunitinib treatment enhances the functional capacity of tumor infiltrating T cells by stimulating IFNγ production and cytolytic activity against the tumor and improves Th1 response after stimulation of PBMC by anti-CD3/CD28 antibodies in mRCC patients." (PMID 23320019, 2012). "Taken together, these results show systemic administration of IL-12 specifically enhances the activation of hepatic T cells, but not splenic T cells, which leads to the further development of IFNγ+ T cells in a RENCA tumor-dependent manner." (PMID 22428016, 2012). "Although adoptively transferred high avidity T cells are efficiently activated to clear tumor in tolerant mice, their cytokine secretion capacity appears limited to IFNγ secretion." (PMID 22359647, 2012). "In a complex series of events, FAP+ cell depletion results in damage to the vasculature and hypoxic tumor necrosis which involves the cytokines interferon gamma (IFNγ) and TNFα." (PMID 24213314, 2012). "Interferon gamma (IFNγ) plays a crucial role in tumor formation and protects host against growth of spontaneous or transplanted tumors." (PMID 22919516, 2012). "Interferon gamma is a pleiotropic cytokine with numerous biological effects, however there is little evidence that it can have a direct cytotoxic effect on tumor cells." (PMID 24710418, 2012). "Recently, fibroblasts were also found to be crucial mediators of IFNγ’s anti-tumor immune effects through down-regulation of VEGF production and induction of angiostasis." (PMID 24213314, 2012). "Another in vivo murine study demonstrated that IL-4-mediated tumor suppression involved the production of the cytokine interferon-gamma (IFN-γ), which supports subsequent findings indicating that IL-4-transfected tumor cell vaccines promoted Th1 immunity." (PMID 22251275, 2012). "Second, HER2/neu-specific Th1 cells can home to the tumor site, secrete IFNγ and other inflammatory cytokines in the tumor microenvironment, and boost the function of macrophages and DCs." (PMID 22397502, 2012). "The cytokine signature of increased IFNγ and reduced IL-10 in the tumor further facilitates antitumor activity." (PMID 22815789, 2012). "We then stimulated splenocytes from tumour-challenged mice for 48 h with IFNγ-treated B16F10 and then stained with anti-CD62L antibodies." (PMID 22506061, 2012). "Overcoming tumor escape by breaking IFNγ resistance in RMS is, therefore, worth to be tested as an adjunct to immunotherapies based on vaccination or adoptive transfer of tumor-reactive cytotoxic effector cells." (PMID 22919516, 2012).
tumor (continued). "Pathologic analysis (via H&E staining) found that there were large areas of necrosis in the tumor tissue treated with Ad-IFNγ, while few necrotic areas were observed in the Ad-LacZ-treated and PBS-treated tumors (data not shown)." (PMID 23272637, 2012). "In patients, HCC-reactive T cells were detected with IFNγ ELISPOT in 4/20 patients before RF ablation upon stimulation of PBMC with lysate of autologous tumor cells obtained either before or after treatment." (PMID 22242035, 2011). "In vitro CD40-activation with IFNγ was required to effectively reprogram tumor-induced M2-like macrophages into activated IL-12 producing M1 cells." (PMID 22176642, 2011). "Systemic treatment with IFNγ was initiated when the faster-growing tumor had reached a size of 6 mm in one dimension, and continued for 28 days." (PMID 21310022, 2011). "Numerous murine studies originally suggested an important role for IFN-γ in tumor immunity: mice with targeted deletion of IFNγ or the Type II IFN receptor have an increased risk of spontaneous and chemically-induced tumors compared to controls." (PMID 24213115, 2011). "We have shown LA treatment induces significant innate and adaptive immune responses, including IFNγ upregulation locally and systemically, indicating these responses to be Th1 and therefore tumor inhibiting." (PMID 21619693, 2011). "This is in agreement with an earlier study, in which we also showed that the anti-tumor effect is mediated by an increase of tumor-infiltrating IFNγ-producing CD8+ T cells." (PMID 21779410, 2011). "IFNγ transcripts have been identified in human tumour neuroglia and human astroglial cell lines and in microglia prepared from athymic nude and scid mice infected with Toxoplasma gondii." (PMID 21453520, 2011). "Tumor T lymphocytic infiltrates from mCCL21-vault treated mice had increased intracytoplasmic IFNγ and reduced IL-10." (PMID 21559281, 2011). "Interferon-gamma (IFN-γ), or type II interferon, is a cytokine critical for innate and adaptive immunity against viral and intracellular bacterial infections and for tumor control." (PMID 22220182, 2011). "WSX1-positive tumor cells reduce not only the number of T cells but also the percentage of T and NK cells secreting IFNγ, similar to the effect of CTLA and PD-1 ligands." (PMID 21559505, 2011). "Upregulation of the Th1 pathway cytokines IL-12 and/or IFNγ within the tumor resulted in tumor killing and directly inhibited tumor angiogenesis." (PMID 21619693, 2011). "CD4 or CD8+ T cells expressing IFNγ, or the IFNγ inducing transcription factor Tbet, are the cells most likely involved at the tumour site." (PMID 21864372, 2011). "When gene expression was analyzed with respect to tumor sizes, both immunosuppressive (CTLA4) and immune stimulatory (IFNγ and TNFα) genes were increased with increasing tumor size." (PMID 22013484, 2011). "Upon α-GC administration serum levels of the cytokines IL-4, IFNγ as products of iNKT cells as well as IL-12 as a product of activated DCs were diminished in tumor-bearing mice, suggesting type-I NKT cells were refractory to stimulation." (PMID 24212972, 2011). "There have been studies indicating that IDO is upregulated in many tumor cell lines only upon treatment with IFNγ and/or other inflammatory mediators." (PMID 22013481, 2011). "IL12 is a potent cytokine, which can have numerous effects on tumor growth, including activation of NK cells, and the induction of IFNγ." (PMID 21674047, 2011). "Tumor -primed Pmel-1 T cells, are capable of killing target cells in the periphery and secrete IFNγ, but are unable to mediate tumor regression." (PMID 21731676, 2011). "A relatively low proportion of tumor infiltrating myeloid cells secrete IL-12 upon a short IFNγ/LPS stimulation (2.7+/−0.8), a proportion quite similar to that of related splenic myeloid cells." (PMID 21633700, 2011).
tumor (continued). "DNMTi effects on the APM and co-stimulatory/inhibitory gene expression in vivo in some tumour cells resemble the impacts of IFNγ on the expression of these genes." (PMID 22015556, 2011). "As indicated by the tumor volumes, IFNγ-treatment diminished the growth rate of pure DSL-6A/C1 tumors in a non-significant manner (columns 5 and 6)." (PMID 21310022, 2011). "Our data indicate that expression of these crucial players in the IFNγ-signalling pathway is increased in tumour cells from the 5AC-treated animals." (PMID 22015556, 2011). "Experimental and computational data together suggest that the tumor cells are less responsive to IFNγ in that they require higher doses of the cytokine for efficient STAT1 activation and growth inhibition." (PMID 21310022, 2011). "Immunohistochemistry was used to detect the expression and the activity of the IFNγ in tumor sections." (PMID 21573215, 2011). "Starting as early as 4 days after tumor challenge, we found that ∼5% of Pmel-1 T cells have detectable levels of IFNγ in the TDLN." (PMID 21731676, 2011). "It was shown that a Th1 response and upregulation of IFNγ is required for the prevention of tumor establishment or the elimination of already established tumors." (PMID 21619693, 2011). "The 5AC treatment also decreased the percentage of the IFNγ-producing spleen cells in the tumour-bearing animals." (PMID 22015556, 2011). "Conversely there is also evidence that TAMs can delay tumour growth by secretion of factors such as nitric oxide and interferon gamma, supporting the view that different areas of the tumour can activate different TAM phenotypes." (PMID 22005011, 2011). "In vivo neutralization of interferon-gamma (IFN-γ) completely eliminated the anti-tumor effects of IL-18 confirming an essential role of IFN-γ as a down-stream mediator of the anti-tumor activity of IL-18." (PMID 21935389, 2011). "On one hand, Tcregs facilitate tumor growth by suppressing activated T cells; on the other hand, they secrete a large amount of the Th1 cytokine IFNγ, which inhibits tumor cell growth and promotes the differentiation of Th1 cells." (PMID 22051182, 2011). "The engagement of NKG2D through coculturing human NK cells with MICA-bearing tumor cells leads to a PI3K-dependent increase of IFNγ secretion by NK cells." (PMID 22046194, 2011). "In particular, it focused on changes of Kupffer cells (or tumor infiltrating macrophages; TAMs) and CD3+ T cells representing innate and adaptive immunity respectively and on IFNγ expression which is associated with Th1 protective immune responses in cancer." (PMID 21619693, 2011). "IFNγ responses to gp10025–33 or TRP2181–188 or to B16 tumor cells were reproducibly higher with DC-B16 zVAD than with DC-B16γ." (PMID 21552572, 2011). "Secretion of IFNγ plays a key role in macrophage activation, inflammation, T helper 1 (Th1) cell responses, tumor surveillance, immunoediting and host defense against intracellular pathogens." (PMID 21559505, 2011). "But the issue remains what happens with this Th17/Th1 cells under tumour influence, if they simply attenuate IFNγ secretion or change into another T cell population." (PMID 20877351, 2010). "The antitumoural properties of IFNγ-activated macrophages have been demonstrated in vitro in experimental murine models of human tumours." (PMID 20529333, 2010). "In particular, we studied the production of Th1 cytokines, namely IFNγ and TNFα, which play an important role in anti-tumor immunity." (PMID 21092174, 2010). "The association of high expression of genes in the Th1 immune response pathways (IL12, IL2, IFNG) with good prognosis is consistent with their putative tumor-inhibitory role." (PMID 21050467, 2010). "TGFβ and TNFRsf1a displayed high expression in both tumor cell compartments, while IL-4 and IFNγ had low expression levels." (PMID 20525400, 2010).
tumor (continued). "The functional inhibition of IFNγ production was reversible by the simultaneous addition of both IL-12 and the high-affinity ligand α-GalCer, thus showing that tumor cells reversibly inhibit iNKT cells." (PMID 20593019, 2010). "The study of Klebanoff also showed that the pre-activation of the T cells allowed Ag-independent release of IFNγ, which in turn acted on tumor cells to induce MHC I, which the authors proposed was key to rendering the tumors susceptible to tumor killing." (PMID 20543982, 2010). "Single agent drugs which are FDA approved for other indications that are effective in mouse TSC tumor models include interferon gamma (IFN-γ), sunitinib, bevacizumab, asparaginase, and tamoxifen." (PMID 20146790, 2010). "We first analyzed the ability of tumor-specific T cells to secrete IFNγ and express CD107 upon restimulation." (PMID 20454561, 2010). "Cyclophosphamide pre-treatment augments the anti-tumor effect by increasing the proliferation of interferon-gamma producing cells in the adoptive host." (PMID 21050466, 2010). "In a small study of tumor patients treated locally or distally with IFNγ-activated monocytes reduction of ascites tumors in two of seven patients occurred only when the monocytes were administered locally (i.p.)." (PMID 20664817, 2010). "Tumor cells respond to IFNγ by suppressing the expression of MMP-9 and MMP-2 genes, which are involved in the invasion and angiogenesis process of malignant tumors." (PMID 20157617, 2010). "We conclude from these findings that tumor cells directly block the production of IFNγ cytokines in iNKT cells." (PMID 20593019, 2010). "Specifically, upon activation with the CD1d ligand α-GalCer, iNKT cells from tumor-bearing mice exhibited a diminished production of both Th2 cytokines and IFNγ." (PMID 20593019, 2010). "Cigarette smoke prevented NK cell activation, as well as perforin and interferon-gamma secretion upon tumour challenge." (PMID 20107494, 2010). "This aberrant iNKT cell activation was correctable by simultaneous addition of the exogenous CD1d ligand α-GalCer and IL-12, and allowed iNKT cells to produce IFNγ in response to tumor cells." (PMID 20593019, 2010). "Activated Vγ9Vδ2 T-cells are known to secrete large amounts of IFNγ and TNFα, very potent anti-tumor mediators in vivo." (PMID 19479075, 2009). "Consistent with the anti-tumor effects of r-hu-IFNγ, Ad-IFNγ produced a significant dose-dependent inhibition of tumor growth in CNE-2 models." (PMID 19216804, 2009). "Further activation of IFNγ-primed macrophages with antibody-coated tumor cells (indicated as RR in the figure) resulted in significantly higher levels of TNFα in presence of DMSO." (PMID 19148288, 2009). "We investigated the activation of several signaling pathways in macrophages in response to antibody-coated tumor targets by stimulating IFNγ-primed peritoneal macrophages with formaldehyde-fixed Rituximab-coated Raji targets for various time points." (PMID 19148288, 2009). "Our data showed that IL-2 signal at priming stage in vitro drove development of CD8+ effector cells which produced greater quantities of IFNγ and Granzyme B when encountered the tumor in vivo." (PMID 19901991, 2009). "STAT1H tumor cells also demonstrate resistance to IFN-gamma (IFNγ), ionizing radiation (IR), and doxorubicin relative to parental B16F1 and low expressors of the IFN/STAT1 pathway (STAT1L genotype)." (PMID 19503789, 2009). "The concentration of IFNγ in tumor was highest (P < 0.05, compared to blood or parenchymal organs), then in liver and kidney (P < 0.05, compared to blood or other parenchymal organs)." (PMID 19216804, 2009). "The results showed that there were more Granzyme B- and IFNγ- producing cells in the tumor in mice receiving P14IL-2 (0 h) than other groups." (PMID 19901991, 2009). "We also showed that selection of the sensitive parental tumor SCC61 against IFNα or IFNγ led to constitutive overexpression of the IFN/STAT1 pathway and development of resistance to IR." (PMID 19503789, 2009).